FOXP3 (forkhead box P3)
Diseases named in the same sentence as FOXP3 in open-access papers (continued):
Sharing a sentence is not in itself a finding about the gene and the disease.
tumor (continued). "In addition, MDSC were reported to induce the development of FoxP3+ regulatory T cells (Treg) in tumor bearing host and to subvert tumor associated macrophages into M2 cells in a cell-contact dependent manner." (PMID 33578808, 2021). "In addition, we outlined the immune landscapes remodeled by the FOXP3-based immune risk score system and revealed the heterogeneity of tumor-infiltrating immune cells in SCLC samples." (PMID 34006632, 2021). "FOXP3 could inhibit or promote HCC by regulating the tumor microenvironment, mutation, post-translational modification or alternative RNA splicing." (PMID 33522955, 2021). "In addition, increases of Tregs and FOXP3 in patients with digestive tract malignancies are associated with a poor prognosis because of an association with tumor immune escape." (PMID 33838641, 2021). "As for the neutrophil and FOXP3-positive cell, previous studies have reported that tumor-associated neutrophil can recruit FOXP3-positive cells through chemokine ligand 2 (CCL)–chemokine receptor-2 (CCR) and CCL17–CCR4 pathways to form immunosuppressive TIME and promote tumor progression." (PMID 34804034, 2021). "The tumor-associated MVARPHI may trigger an increase in the number of Foxp3 (+) Treg populations in tumors, thereby promoting the development of HCC." (PMID 34869376, 2021). "In vivo studies using mouse models showed that the absence of EGFR and its downstream signaling by genetically deleting the EGFR in tumour cells led to a significantly diminished infiltration of FoxP3 expressing Treg cells in EGFR deficient tumours in comparison to wt EGFR tumours." (PMID 35052732, 2021). "Taken together, these data show that the presence of CD3+, CD8+, or FoxP3+T lymphocyte infiltrates in the tumor margins are associated with the pathogenesis of CRC, but only high Foxp3+ T lymphocyte infiltrations in the tumor invasive margins are inclined to indicate favorable prognosis." (PMID 34440038, 2021). "FOXP3 is the most specific marker for Treg cells and, often associated with a negative impact on survival in several types of cancer, is likely to have an important role in suppressing anti-tumor immunity." (PMID 34876047, 2021). "Also, biopsy studies of people with PC have shown that the infiltrated TILs in the tumor tissue are often FOXP3+ which are associated with a bad prognosis." (PMID 34868907, 2021). "Cyclooxygenase-2 (COX-2) inhibition can potentiate the efficacy of anti-VEGF therapy by reversing hypoxia-induced EMT and promoting an immune landscape that increases tumor-associated CD8+ T cells while reducing FoxP3+ T cells and FasL expression on the tumor endothelium." (PMID 33436044, 2021). "We also evaluated tissue immune infiltrates using duplex immunohistochemistry, which showed much greater densities of CD8+ and FOXP3+ cells in tumor compared to high-risk and healthy control tissues, concordant with the NanoString-based cell abundance estimates." (PMID 33863341, 2021). "The expression levels of FOXP3 in CD8+ T cells were found to be positively associated with the stage of tumour in OC patients which implies that the OC TME may have the capacity to convert CD8+ effector T cells into CD8+FOXP3+ suppressor cells in vivo." (PMID 33808294, 2021). "We aimed at analyzing the immune cell population (CD8 and FoxP3, a marker for Treg cells) by means of immunohistochemistry (IHC); and identifying associations of the immune population patterns with the β-catenin status and origin of the tumor." (PMID 34257613, 2021). "After NACT, it is the combination of high CD8+ TILs which recognize foreign antigens on tumor cells and kill it by inducing the release of perforin and granzyme, associated with decreased FOXP3+ TILs, which have a critical role in suppressing anti-tumor immunity, leading to improved survival." (PMID 32852603, 2021).
tumor (continued). "HLA class II on TILs, PD-L1 on TILs, CD4, and FOXP3 were enrolled in the immune risk model, which categorized patients into high-risk and low-risk groups and had better power for predicting the recurrence than tumor stage." (PMID 34362829, 2021). "After being secreted by activated T cells, monocytes, and/or tumor-associated stromal cells, IL-3 could induce a concomitant increase in the percentage of both Foxp3+ Tregs and IL-2 secreting Th cells in a dose-dependent manner." (PMID 33868318, 2021). "Our results showed that enriched IL-21+ cells and PD-L1 expression were positively associated with FOXP3+ cell infiltration and that high expression of IL-21 and PD-L1 correlated with advanced tumor stage and poor overall and disease-free survival in patients with HNSCC." (PMID 34026621, 2021). "A more recent study comparing pre-treatment and biopsy material obtained from rectal tumours 7 days after irradiation showed that a high density of CD4+ and FoxP3+ cells pre-treatment was significantly associated with tumour shrinkage, and that this link was most pronounced in the 7 day biopsies." (PMID 34321074, 2021). "The majority of CD4+ T-cells are suppressive CD25+ forkhead box P3 (FOXP3)+ regulatory T-cells (Tregs), which are themselves recruited by tumor B-cells; it has been suggested that higher numbers of tumor-infiltrating FOXP3+ cells are associated with better response to H. pylori eradiation therapy." (PMID 34298992, 2021). "Tumor implantation caused a dramatic increase in pulmonary CD4+CD25+Foxp3+ Tregs 21 days later, and this increase was unaffected by treatment with BEMPEG (3.1% ± 0.8, 3.1% ± 0.9 and 0.8% ± 0.1 of live cells for vehicle, BEMPEG and no tumor groups, respectively)." (PMID 33152115, 2021). "Tumor-associated neutrophils and macrophages are associated with poor prognosis in a variety of cancer types and a risk signature based on the presence of tumor-associated neutrophils and FOXP3+ regulatory T cells (Tregs) in extrahepatic CCA has been identified." (PMID 36045705, 2021). "Taken together, our data support a role for LAIR2 expression in tumor-associated Foxp3+ Treg cells." (PMID 35008369, 2021). "Moreover, miR-155 is essential for the development of MDSC and also for MDSC-mediated modulation of CD4+Foxp3+ regulatory T cells, indicating that MDSCs are associated with miR-155 to promote tumor growth." (PMID 33133086, 2020). "More detailed immunophenotyping of tumor leukocyte populations revealed no consistent changes in the proportion of CD19+ B cells, F4/80+ macrophages, CD11b+Ly6G+ myeloid cells, NK cells, or CD4+CD25+FoxP3+ regulatory T cells associated with loss of Raptor from tumor ECs." (PMID 32759497, 2020). "Moreover, the expression of B7-H4 in tumor-associated macrophages was correlated with Foxp3+ regulatory T cells (Tregs)." (PMID 33062039, 2020). "Less explored is the impact Foxp3 allelic variants may have on tumor incidence, progression and therapy." (PMID 31729760, 2020). "A previous study with 93 cases showed that a high pretherapeutic CD8+/FOXP3+ intraepithelial lymphocyte ratio was associated with favorable tumor regression, which is consistent with our finding of a specific association between the density of CD8+ TIL and the treatment response." (PMID 33442477, 2020). "The finding that a high density of infiltrating FOXP3+ Treg cells was associated with unfavorable outcome in many cancers supported the theory that tumor‐infiltrating FOXP3+ Treg cells were suppressing the anti‐tumor response and enabling cancer immune escape." (PMID 32377339, 2020). "In addition to nTregs and iTregs that develop from naive precursors, suppressive IL-17A+Foxp3+ and ex-Th17 Foxp3+ Tregs are sources of tumour-associated iTregs." (PMID 32680511, 2020). "At D16 post tumor implantation, using flow cytometry analysis, we found that the deficiency of Bcl6 results in an impairment of Treg cells, evidenced by the decreased proportion and absolute number of Foxp3+CD4+ T cells." (PMID 32477338, 2020).
tumor (continued). "In addition, RIG‐I levels were significantly linked to increased FoxP3 expression, suggestive of tumor infiltration by suppressor cells of the Treg lineage (p = 0.010)." (PMID 31800094, 2020). "Notably, we confirmed in our study a prognostic benefit of FoxP3+ T cell infiltrates which stands in contrast to previous meta-analyses suggesting that tumor-infiltrating FoxP3+ T-cells are associated with poor clinical outcomes in solid cancers." (PMID 32099066, 2020). "Ultimately, it is crucial to note that while CD8+ T cells are an essential component of tumor immunity, a number of additional immune cell types have shown prognostic associations in cancer such as FOXP3+ Treg, CD20+ B-TIL as well as myeloid cells such as M1 and M2 macrophages." (PMID 33013886, 2020). "The immune infiltrate was characterized by the presence of CD3+ cells (T-cells) and CD163+ cells (M2-like tumor associated macrophages, M2-TAMs), regarded as immunosuppressive and pro-tumoral cells, and FoxP3+ cells (activated T regulatory cells, Treg) in serial and consecutive sections." (PMID 32899203, 2020). "In particular, combinatorial therapeutic approaches that re-educate the TME by limiting the accumulation of immunosuppressive immune cells, such as Foxp3 regulatory T cells (Tregs) and tumor-associated macrophages (TAMs), while promoting CD8+ and CD4+ effector T cell activity is critical." (PMID 32849557, 2020). "Recently, lower proportions of PD-1 positive cytotoxic T cells (CD3+CD8+FOXP3−) have been associated with poorer survival, with longitudinal analyses of the tumour-infiltrating T-lymphocytes suggesting large changes in the microenvironment over the course of the disease." (PMID 32070062, 2020). "Furthermore, endothelial IDO expression was associated with reduced CD8+ T-cells and increased FoxP3+ Tregs in the tumor microenvironment." (PMID 33072086, 2020). "Flammiger et al45 marked Treg cells in PCa tissues using FOXP3 immunohistochemistry, and the results showed that PSA recurrence‐free survival was decreased in patients with a higher density of Treg cells, and a high level of FOXP3+ Treg cells was associated with advanced PCa tumor stage." (PMID 31355524, 2019). "These cells include CD4 FOXP3+ regulatory T cells (Tregs), tumor-associated macrophages (TAMs) and myeloid-derived suppressor cells (MDSCs); all these subsets are capable of inhibiting effector T cell anti-tumor immune response, although with different mechanisms." (PMID 31060225, 2019). "Similarly to PD-L1, IDO1 is overexpressed in different tumors, and is associated with the activation of Foxp3+ Tregs and the down-regulation of cytotoxic cellular immunity in the tumor microenvironment." (PMID 31412566, 2019). "However, the intratumoral CD8 to FOXP3 ratio showed a trend to be lower in BRCA2-mutated tumors suggesting a more suppressed tumor immune microenvironment." (PMID 31549213, 2019). "Likewise, we recently demonstrated that a high number of FoxP3+ Tregs in tumor micro-environment is associated with longer overall and recurrence-free survivals of HNSCC patients." (PMID 30781400, 2019). "In the current study, we showed that in HCCs, higher percentage of intratumoral Treg cells was positively correlated with lower Foxp3 promoter methylation, and both of them were associated with higher tumor grade, larger tumors, and poor prognosis of the patients." (PMID 31006654, 2019). "Another relevant point lies in the location of mutated FOXP3 protein in different tumor cells." (PMID 30782783, 2019). "The inhibitory activity did not require a direct cell-to-cell contact, but was mediated by cytokine secretion by tumor cells (IL-15 in particular) that caused a de novo functional differentiation of lymphocytes towards a T-regulatory immunophenotype (FOXP3+ CD4+ T-cells)." (PMID 31383005, 2019). "Moreover, a tumor cell vaccine associated with FOXP3 gene silencing can improve the efficacy of therapeutic anti-tumor vaccination." (PMID 31547627, 2019).
tumor (continued). "Additionally, the dysfunction of TRAF6‐deficient Tregs in our tumor experiments was found to be associated with this uncharacteristic distribution of FOXP3 protein." (PMID 30886050, 2019). "Due to the ability to inhibit anti-tumor immunity, tumor-infiltrating Foxp3+ Tregs were associated with poor prognosis, but recently, it has been shown that Foxp3+Tregs could improve survival in some tumors." (PMID 31086100, 2019). "Similarly, accumulated CD4+CD25+FoxP3+ Tregs was also found in both peripheral bloods and tumor tissues in Epstein–Barr virus-associated GC." (PMID 30988066, 2019). "An immunoregulatory-rich tumor microenvironment was associated with lower mean of CD68+ pSTAT1+ cell numbers (mean 163 cells/mm2 for FOXP3+/GrB ratio >1.5 vs. mean 270 cells/mm2 for FOXP3+/GrB ratio ratio <1.5, p = 0.028, Mann-Whitney test)." (PMID 31481738, 2019). "Analysis with regard to the numbers of Tregs indicated that both the “excluded” and the “inflamed” groups were not homogenous, but that they can be further stratified according to FoxP3+ Treg cell counts, underlining an important immune modulatory role of Tregs in the tumor microenvironment." (PMID 31546872, 2019). "For each factor, a score of 1 was associated with a good prognosis meaning that the number of FoxP3+ Treg infiltration in the ST compartment is higher than 63.15, the tumor stage is at early stage I or II, and tumor histological grade reported differentiated tumors." (PMID 30781400, 2019). "In order for this to happen, T-lymphocytes must be able to infiltrate the tumor and mount appropriate responses and higher numbers of CD3+, CD8+ and FOXP3+ tumor infiltrating lymphocytes (TILs) are associated with a favorable outcome in in several malignancies, including HNSCC." (PMID 30211111, 2018). "Thus tumour suppressors, such as FOXP3, which is mutated or lost in many cancer tissues, play an important role in maintaining normal tissue homeostasis." (PMID 29963231, 2018). "However, over-expression of Δ3,4-FOXP3 showed a remarkable loss of tumor suppression than full-length FOXP3 (P = 0.004 and P = 0.012 for Hep3B and 97H, respectively)." (PMID 28903735, 2017). "In addition to reducing the Foxp3+ T cells in the tumour microenvironment, our data reveal that the Th17-supporting transcription factor RORγt profoundly alters the phenotype of tumour-associated Foxp3+ T cells." (PMID 28290453, 2017). "However, in human CRC, high density of tumor-infiltrating FoxP3+ Tregs was shown to associate with worse survival in several studies, while some other studies reported opposite results." (PMID 29088871, 2017). "Thus depression of CD4+CD25+FoxP3+ numbers was associated with the capacity to control tumours in the gastrointestinal tract of T. muris infected mice." (PMID 28650985, 2017). "This new tumor microenvironment becomes comprised of immunoregulatory populations, including FoxP3+ regulatory T cells, tumor associated macrophages, and myeloid derived suppressor cells, which actively work to suppress effector T cells from mediating their cytolytic functions." (PMID 29065490, 2017). "Considering FOXP3 dual role in tumor microenvironment, investigation of polymorphisms and their possible associations with cancer may shed light on the molecular cancer pathogenesis and open new perspectives to susceptible individual screening." (PMID 28713192, 2017). "This prolonged condition also generates an immuno-suppressive environment by recruiting suppressor cells, including CD4+CD25+Foxp3+ regulatory T cells (Treg), myeloid-derived suppressor cells (MDSCs), tumor-associated macrophages (TAMs), N2-polarized neutrophils, and regulatory/tolerogenic DCs." (PMID 28212561, 2017). "Our data indicates that reduced Runx1 transcriptional activity downregulates Rspo3 oncogene expression, upregulates GJA1 tumor suppressor gene expression, significantly delays tumor cell migration and wanes cell number, in a susceptible manner to Foxp3's stalling activity." (PMID 26735887, 2016).
tumor (continued). "A series of studies have illustrated that the mutation or loss of Foxp3 might lead to a high rate of tumor formation, such as developing in mammary or prostatic epithelial tissues, which indicated Foxp3 as an oncosuppressive factor." (PMID 27457382, 2016). "Moreover, CD4+CD25+Foxp3+Tregs are considered as suppressors in immune surveillance and anti-tumor immunity, which are also proved associated with HCC invasiveness." (PMID 27439521, 2016). "Epithelial cell adhesion molecule-positive (EpCAM+) CTCs are a proven independent risk factor for HCC recurrence in our previous study, while immune suppressive CD4+CD25+ regulatory T cells (Treg) intra-nuclear expressing Foxp3+ are associated with tumor immune tolerance and immune escape." (PMID 27439521, 2016). "High post-NAC tumour levels of FOXP3+ T cells, IL-10, and IL-17 were associated with a failed pCR." (PMID 27777963, 2016). "TGF-β-induced immunosuppression occurs when tumor cells escape attack by the immune system through various mechanisms, including interaction with CD4+CD25+Foxp3+ regulatory T cells (Treg cells), tumor-associated macrophages, tumor-associated neutrophils (TAN), and T helper 17 (TH17)." (PMID 26779375, 2015). "As CD4+ T-cells comprise a heterogeneous group in that there are both tumor-reactive and suppressive populations, we set out to examine whether concomitant high Foxp3+ T-cell density contributed to its association with high-PD-L1-expressing metastases." (PMID 26317902, 2015). "Higher average numbers of FoxP3+ cells were also significantly associated with larger tumor size." (PMID 26462021, 2015). "One of our most striking observations was that the CD8:Foxp3 T-cell ratio was inversely correlated with PD-L1 in metastatic lesions, such that higher tumor PD-L1 expression was associated with a low CD8:Foxp3 ratio (p = 0.021 by t-test, and p = 0.005 by Chi square test)." (PMID 26317902, 2015). "Furthermore, in experimental animal models, the loss of FOXP3 expression in mammary and prostatic epithelial tissues leads to tumor formation." (PMID 26305693, 2015). "A possible explanation could be a significant association between HLA class I tumor expression and Foxp3+ tumor infiltration in our cohort." (PMID 24997850, 2014). "A low CD8+ to-FoxP3+ ratio, however, is associated with tumor infiltration of FoxP3+ cells." (PMID 25365237, 2014). "In addition, forkhead box 3 (Foxp3), a transcription factor associated with T cell tolerance, is expressed in tumor cells and plays a role in the immune evasion of cancers." (PMID 24932293, 2014). "All the studies consistently shown high density of tumor-infiltrating FoxP3+ T cells have been associated with poor survival and high recurrences in HCC, consistent with the initial hypothesis that FoxP3+ T cells inhibit antitumor immunity." (PMID 24827118, 2014). "In addition, the GITR-GITRL interaction has been known to attenuate Treg cell function via the loss of Foxp3 expression as well as enhance tumor-specific effector CD4+ and CD8+ T cell functions." (PMID 25105508, 2014). "Likewise to FoxP3, tumor cell associated expression of L1CAM has been shown to confer immunosuppressive functions to CD4+ T cells in vitro (unpublished observations)." (PMID 24797069, 2014). "When we combined our markers, patients showing the worst prognosis were patients with tumors bearing 2 or 3 negative prognostic markers; patients with loss of HLA class I tumor expression, weak HLA-G tumor expression and low tumor infiltration with Foxp3+ cells." (PMID 24997850, 2014). "Consequently, increased infiltration of Foxp3+ T cells is often associated with a poor prognosis and accelerated tumor progression." (PMID 23874342, 2013). "Moreover this enhancement in anti-tumor immunity is associated with elimination of FOXP3-expressing intra-tumoral Tregs." (PMID 23341929, 2013). "Furthermore, some other studies suggest that a high frequency of tumor infiltrating Foxp3+ Treg is associated with favourable prognosis in CRC." (PMID 23382847, 2013).